TLR9 (toll like receptor 9)
Diseases named in the same sentence as TLR9 in open-access papers (continued):
Sharing a sentence is not in itself a finding about the gene and the disease.
tumor (continued). "The ability to modulate both immune system response and tumor cells behavior by activating TLR-9 represented, thus, an attractive therapeutic option." (PMID 28548068, 2014). "The specificity of the immune therapy requires, however, a clear understanding of how TLR9 expression affects tumor immunity." (PMID 25101078, 2014). "Berger and colleagues determined that higher levels of TLR9 expression correlated with more severe tumor grade." (PMID 25101083, 2014). "Future investigations are expected to be more focused on the combination of TLR-9 agonists with other immunotherapeutic agents, such as vaccines, as combined approaches are more likely to hamper tumor attempts of eluding immune response." (PMID 28548068, 2014). "For instance, the activation of TLR-9 pathway in lung cancer cells enhanced their metastatic potential by indirectly down-regulating tumor suppressive microRNA, such as miR-7." (PMID 28548068, 2014). "The TLR9 agonist CpG has been shown to eradicate murine intracranial glioma when subcutaneously administered with tumor lysate and effector T cells." (PMID 25411122, 2014). "Some analogs of nucleic acids that activate TLR7 and TLR9 have been used in clinical trials to improve anti-tumor immune response against solid tumors." (PMID 24904578, 2014). "The addition of anti-IL-10R to TLR9 agonist CpG also exhibited robust anti-tumor activity exceeding by far that of CpG alone, and elicited anti-tumor immune memory." (PMID 24624132, 2014). "In this review article, we will report about the role of TLR-9 agonists in cancer therapy with a description of the immune system modulation, as well as of direct tumor cell-related effects shown in preclinical studies and clinical trials." (PMID 28548068, 2014). "Consistently, in vitro scratch essays revealed the increased migratory capabilities of tumor cells expressing higher TLR9 levels (in both ovarian and breast tumor cells)." (PMID 25101083, 2014). "CC lines significantly increased MFI of TLR-3 and TLR-7 in comparison with the LPS group, whereas, for TLR-9, only tumor cells infected with viruses HeLa and SiHa, induced an increase in MFI (P < 0.05)." (PMID 25309919, 2014). "Here, we show that in vivo treatment with TLR9 agonist CpG-ODNs also induces modulation of several miRNAs in tumor cells." (PMID 23484053, 2013). "TLR9 staining scores were compared with tumor stage, Gleason score and prostate-specific antigen (PSA) concentration prior to treatment and progression-free survival." (PMID 23761830, 2013). "Suppression of TLR9-mediated IFNA1 secretion from PBMCs by adrenoceptor stimulation reduced the lytic activity of NK cells on K562 tumor cells." (PMID 23724117, 2013). "We revealed that, although decreased TLR9 expression in TNBC cells results in decreased invasion when the tumor cells are in normoxia, the cells become highly invasive in hypoxia." (PMID 24273604, 2013). "Interaction of CpG-ODN with TLR9 can result in the generation of both innate and adoptive immune responses, either of which have the potential to significantly impact tumor growth." (PMID 23360557, 2013). "We previously showed that TLR9-expressing cells in the tumor microenvironment can sensitize cancer cells to DNA-damaging cisplatin treatment by down-modulating genes involved in DNA repair." (PMID 23484053, 2013). "We recently reported that peritumoral CpG-ODN treatment, activating TLR-9 expressing cells in tumor microenvironment, induces modulation of genes involved in DNA repair and sensitizes cancer cells to DNA-damaging cisplatin treatment." (PMID 23484053, 2013). "The anti-tumor efficacy of chloroquine was studied in an orthotopic mouse model, using control siRNA and TLR9 siRNA MDA-MB-231 cells." (PMID 24273604, 2013). "These novel TLR9 agonists have been shown to induce potent Th1-type immune responses and a broad spectrum of antitumor activity in a number of tumor models." (PMID 22238604, 2012).
tumor (continued). "Significant tumor growth retardation was seen in mice treated with RT+TLR9 agonist as compared with untreated mice (p<0.01)." (PMID 22666458, 2012). "Further studies showed that checkpoint suppressor 1 (Ches1) was a dominant direct target for miRNA-574-5p to confer the TLR9 signaling enhanced tumor progression." (PMID 23133627, 2012). "Consistently, we further showed that the expression of TLR9 and miR-574-5p was higher in clinical tumor tissues and exerted a positively correlation." (PMID 23133627, 2012). "At a serum dilution of 1∶1600, RT+TLR9 agonist induced a significant level of tumor-reactive antibody, as compared with untreated (n = 8, p<0.05) and TLR9 agonist alone cohorts (n = 8, p<0.05)." (PMID 22666458, 2012). "TLR9 agonist induces the proliferation of TLR9-expression splenocytes in mice bearing an ectopic 3LL footpad tumor." (PMID 22666458, 2012). "The tumor treated with RT alone regrew after 14 days while tumor treated with RT+TLR9 agonist remained stabilized." (PMID 22666458, 2012). "TLR9 agonists have been widely used in cancer therapy due to its ability of inducing potent anti-tumor immune response." (PMID 22666458, 2012). "TLR9 agonist improved the survival of mice beyond 28 days post-AIR (p<0.008) with significant reduction of tumor growth (p<0.0001)." (PMID 22238604, 2012). "Consistently, we found that over-expression of Ches1 in 95D cells effectively impaired their enhanced tumor progression induced by TLR9 signaling in nude mice (p<0.05)." (PMID 23133627, 2012). "Animals treated with RT or TLR9 agonist alone also exhibited initial tumor growth retardation in the first two weeks post-treatment but the tumors eventually regrew after treatments were stopped." (PMID 22666458, 2012). "RT increased the deposition of mouse IgG auto-antibodies on the tumor tissue, as noted by increased immunofluroscence in RT and RT+TLR9 agonist tumor cohorts." (PMID 22666458, 2012). "Surprisingly, RT+TLR9 agonist still induced significant tumor growth retardation as compared with untreated mice (p<0.01)." (PMID 22666458, 2012). "RT+TLR9 agonist therapy induced tumor-specific IgG auto-antibodies, and stimulated proliferation and activation of TLR9-expressing B cells, pDCs and NKDCs." (PMID 22666458, 2012). "Blockade of CTLA4 or PD-1 in combination of TLR9 agonist CpG ODN treatment overcomes immune tolerance in tumor bearing mice with improved long-term survival, increased tumor-specific effector T-cell population and decreased Treg cell levels." (PMID 22737174, 2012). "The unique ability of NKDCs to directly lyse tumor cells provides another anti-tumor pathway mediated by TLR9 agonist." (PMID 22666458, 2012). "A strong tumor-specific humoral immune response (titer: 1/3200) with deposition of mouse IgG auto-antibodies in tumor tissue were found in wildtype mice, whereas the number of tumor infiltrating NKDCs increased in B−/− mice following RT+ TLR9 agonist therapy." (PMID 22666458, 2012). "RT+TLR9 agonist treatment induced a potent IgG antibody response against 3LL tumor, as analyzed by indirect ELISA with 3LL tumor lysate coated as antigen on the ELISA plates." (PMID 22666458, 2012). "RT+TLR9 agonist treatment induced a significant infiltration of NKDC in the tumor tissue while TLR9 agonist and RT alone induced a slight infiltration of only conventional DCs." (PMID 22666458, 2012). "In this study, we have shown that combined RT and TLR9 agonist administration has synergistic anti-tumor effect in mice bearing a murine lung adenocarcinoma with improved primary tumor growth retardation and reduction of systemic pulmonary metastases." (PMID 22666458, 2012). "When the TLR4/TLR9 agonist complex is applied after tumor cell inoculation, it is unable to reverse the immunosuppressive tissue environment induced by tumor cells." (PMID 21931823, 2011).
tumor (continued). "In current study, we assessed the efficacy of an immunotherapeutic regimen consisting of the TLR4 agonist EC-LPS plus the TLR9 agonist CpG ODN against tumor metastasis." (PMID 21931823, 2011). "The triggering of TLR4 and TLR9 on prostate cancer cells has also been shown to promote tumour cell proliferation through increased NF-κB activation." (PMID 20145615, 2010). "The TLR9 agonist CpG is increasingly applied in preclinical and clinical studies as a therapeutic modality to enhance tumor immunity." (PMID 20020049, 2009). "Immunohistochemistry (IHC) revealed strong TLR9 protein expression within tumor cells of tissues and cell lines." (PMID 15631627, 2005). "Treatment with LNP/pNC in TLR9-KO mice were still to inhibit tumor growth." (PMID 41424839, 2026). "Real time SERS in vivo imaging enables detection of dynamic longitudinal changes in CD8 and VEGFR2 in response to STING + TLR9 (stimulator of interferon genes + toll like receptor 9) immunotherapies, a treatment that increases tumor immunogenicity through a type I interferon response." (PMID 41543356, 2026). "In a study employing B16-OVA melanoma, Panc-OVA pancreatic, and TRAMP-C1 prostate cancer mouse tumor models, the simultaneous administration of an ISCOMATRIX vaccine with poly(I:C) and a TLR9 agonist resulted in a significant reduction in tumor growth across all models." (PMID 41154585, 2025). "Further it has been shown that administration of anti-tumor immunotherapy specifically, peritoneal injection of toll like receptor 9 (TLR9) agonist CpG oligodeoxynucleotide combined with the TGF-β2 inhibitor TIO3 enhanced the presence of trogocytic neutrophils within the tumor nodules." (PMID 41181711, 2025). "Reducing TLR9 expression effectively sensitizes tumor cells to targeted PD‐L1 therapy." (PMID 40727252, 2025). "TLR4 signaling promotes tumor growth, while TLR7, TLR8, and TLR9 signaling may exert anti-tumor effects." (PMID 40948759, 2025). "A dual-action lipid nanoparticle (dual-LNP) that co-delivered VISTA-specific siRNA and a TLR9 agonist (CpG) showed superior anti-tumor efficacy, effectively silencing VISTA expression and enhancing cytotoxic T cell responses in melanoma and colon carcinoma models." (PMID 41233805, 2025). "Interestingly, we found that TLR9 expression was colocalized with CD163+ macrophages in tumor tissues from HCC patients." (PMID 40038250, 2025). "CpG oligodeoxynucleotides (ODNs) represent a promising class of immunotherapeutic agents that activate the innate immune system through the Toll-like receptor 9 (TLR9) signaling pathway and exert anti-tumor effects by reversing the immunosuppressive tumor microenvironment." (PMID 40740229, 2025). "Furthermore, TLR9 activation increases the microglial phagocytic machinery as a result of contact between microglia and tumor cells, leading to tumor cell death." (PMID 41268299, 2025). "TLR9 pathway plays a vital role in macrophage polarization and tumor progression." (PMID 40038250, 2025). "In turn, this may lead to the activation of TLR9 and upregulation of NF-κB contributing to tumor progression and poorer survival." (PMID 40437466, 2025). "Moreover, TLR9-mediated tumor progression involves the implication of various chemokines, particularly CCL2 and CCL5, along with matrix metalloproteinases (MMP), such as MMP-2 and MMP-9." (PMID 41157253, 2025). "Given that mouse tumor macrophages, along with neutrophils, express TLR9, it is possible that such treatment could also impact macrophage activity." (PMID 40885734, 2025). "Notably, a sex-dependent response emerged in mice vaccinated with MUC1 C3-liposomes with TLR agonists (TLR4, TLR7/8, and TLR9); male mice exhibited greater tumor suppression than females." (PMID 40284463, 2025). "Additionally, the release of HMGB1 by NETs activates TLR9 signaling in tumor cells, enhancing their metastatic potential." (PMID 40995363, 2025).
tumor (continued). "TLR9 activation may also contribute to the establishment of an immunosuppressive tumor microenvironment, thereby facilitating tumor progression." (PMID 38903515, 2024). "As a result, our previously documented maintenance of tumor development following AdjFluVx treatment could be attributed to TLR4 and TLR9 activation, supporting an immunosuppressed tumor microenvironment." (PMID 38476365, 2024). "Notably, the administration of a tumor-targeting TLR9 agonist, PIP-CpG, induced a systemic T cell-mediated immune response, promoting the regression of existing mammary tumors and eliciting an immune memory response that delayed the growth of new tumors." (PMID 39123407, 2024). "Furthermore, studies have suggested a potential role for TLR9 upregulation in modulating the tumor microenvironment and immune response." (PMID 39123407, 2024). "On the other hand, immunomodulatory agonists for TLR2 and TLR9 can enhance tumor immunity." (PMID 38390872, 2024). "Alternatively, the design of TLR9 agonists that stimulate responses in specific cell types (tumor vs. immune cell) could help address this point." (PMID 38201300, 2024). "Finally, the expression of PDGF-DD by tumor cells should be taken into account in clinical trials using TLR9 agonists, such as CpG-ODN, as adjuvant therapy." (PMID 39020402, 2024). "It has been proposed that fungal toll-like receptors (e.g., TLR2/TLR9), especially when compounded by a cytokine storm, may shift the immune system into an activated tumor microenvironment stimulating antileukemic effects." (PMID 39011219, 2024). "Given that we detected significantly more circulating CD8+ than CD4+ T cells, it is likely that systemic TLR9 stimulation boosts global immunity, which consequently may act on the tumor." (PMID 38201300, 2024). "The TLR9 agonist was used as an additional anti-tumor agent to activate the innate immune system." (PMID 39339217, 2024). "Furthermore, TLR9 agonists have also undergone extensive research for their potential use in tumor treatment, either as standalone therapies or in combination with other agents." (PMID 38933262, 2024). "Healthy prostate tissue is rich in mononuclear myeloid cells and T cells, so TLR9 stimulation in these resident cells could promote cytokine responses to create a tumor-suppressive microenvironment and inhibit naïve tumor growth." (PMID 38201300, 2024). "Compared with those in normal cells, TLR9 in human BC cell lines had the highest intracellular expression, and its aberrant expression in tumor cells might promote tumor growth and invasion." (PMID 38685971, 2024). "However, the TLR9 pathway stimulated by radiotherapy, cell death, and CpG release, can also induce tumor progression, angiogenesis and invasiveness in cervical cancers through the activation of the NF-κB and STAT3 transcription factors." (PMID 38397187, 2024). "This suggested that the in vivo TLR9 response probably invoked a tumor-suppressive immune response, rather than directly causing the cell death of RM1 cells." (PMID 38201300, 2024). "Indeed, TLR9 agonists can enhance antitumor immunity by reprogramming the tumor microenvironment and increasing the tumor-suppressive potential and/or cytotoxic activity of innate and adaptive immune cells, leading to immune rejection of solid tumors." (PMID 38201300, 2024). "Activation of TLR9 in OSCC using CpG‐ODNs stimulated tumor cell proliferation." (PMID 38685971, 2024). "Our data demonstrate that the TLR9-mediated inhibition of tumorigenesis in our model is likely due to shifting the tumor microenvironment in favor of antitumor immunity in the early stages of tumor development." (PMID 38201300, 2024). "There is a growing body of preclinical evidence that agonists targeting TLR3, TLR5, TLR7/8, or TLR9 in combination with RT may lead to enhanced anti-tumor immunity." (PMID 37112730, 2023).
tumor (continued). "TLR-9-activated B cells played a central role in generating CD8 T cells with potent anti-tumor capacity in vitro, because depletion of B cells from the CpG-treated pmel-1 cultures led to deficient CD8 T cell responses in B57L/6 mice suffering from melanoma after injection." (PMID 36969196, 2023). "Additionally, TLR9 activation has been shown to sensitize tumor cells to apoptosis, resulting in tumor growth arrest." (PMID 37781382, 2023). "It has been established in previous study that intratumoral administration of TLR9 agonists may increase OX40 expression on tumor infiltrating CD4+ T helper cells." (PMID 37700338, 2023). "A complementary experiment was carried out comparing effects of CpG-ODN with a control-ODN to investigate whether observed effects with CpG on CT26 tumor are dependent on TLR9 involvement." (PMID 38292484, 2023). "Moreover, the high expression of TLR9 in ovarian cancers leads to increased disease severity, poor survival, increased tumor grade, and metastasis." (PMID 37822929, 2023). "We further show that CpG-conjugated EVs can significantly improve the processing and presentation of EV-encased antigens by DCs, which could be attributed to the timely stimulation of TLR9 on endosomes during the endocytosis of tumor EVs." (PMID 38052869, 2023). "Moreover, the combined administration of TLR7 and TLR9 agonists with PD-1 blockade in HNSCCs suppresses tumour growth and progression related to TAMs and CD8+ T cell activation and increases the ability of DCs to gain a mature phenotype and migration." (PMID 36980527, 2023). "TLR-9 impacts tumor development and progression through various molecular mechanisms, such as activation of immune response, induction of apoptosis, modulation of angiogenesis, and regulation of tumor cell proliferation and survival." (PMID 38090147, 2023). "Integrating TLR-9 profiling with other molecular markers could enable tailored treatments that capitalize on individual immune dynamics and tumor characteristics." (PMID 37894471, 2023). "Most importantly, in the areas of tumor hypoxia, elevated levels of Tlr9 are also observed." (PMID 38081853, 2023). "TLR-9 can influence the angiogenesis that is required for tumor growth and metastasis." (PMID 38090147, 2023). "Increased levels of soluble TLR-9 in GC patients compared to healthy controls may indicate increased immune activation in the tumor microenvironment." (PMID 37894471, 2023). "To this end, we have treated tumor-bearing mice with two different doses of the TLR9 agonist, 25 and 50 μg, to assess also whether there was a dose-dependent effect." (PMID 37365634, 2023). "Targeting of TLR9 agonist to the tumor tissue is thought to enable the priming of antigen-specific T cells in the draining lymph nodes, to promote the tumor infiltration with effector cells and to disable immune checkpoints in the tumor tissue leading to efficient anti-tumor responses." (PMID 36913398, 2023). "Overall these data indicate that the TLR9 agonist acts as an in situ anti-tumor vaccine, activating an innate immune response sufficient to suppress local tumor growth while inducing a systemic adaptive immunity with selective expansion of CD8 T cell clones, which are needed for the abscopal effect." (PMID 37365634, 2023). "Currently, several preclinical and phase I/II studies also indicate that the administration of CpG oligodinucleotides (ODN), a TLR9 agonist, activates tumour-draining lymph node DCs and enhances the production of IFN-α/β cytokines, resulting in T cell activation." (PMID 36980527, 2023). "Cell-free DNA sensing by TLR9 has dual-faced effects on tumor cells." (PMID 36359370, 2022). "In this work, we have analyzed tumor samples from a cohort that included 30 patients from Argentina and investigated possible connections among the expression levels of TLR9, 4 and 2, the consumption habits of the patients and CD8+T cell infiltration by IHC, regardless of their HPV status." (PMID 35990685, 2022).